WT1 (WT1 transcription factor)
Diseases named in the same sentence as WT1 in open-access papers (continued):
Sharing a sentence is not in itself a finding about the gene and the disease.
cancer (continued). "Gain-of-function and loss-of-function approaches have been used to investigate the role of WT1 and its effect on EMT marker expression and cancer cell migrations." (PMID 35465313, 2022). "In this study, WT1 and SMAD4P130L expressions in EpCAM+ cancer cells were found, and the existence of CD8+ T cells, which respond to cancer antigens in MPE samples, was clarified." (PMID 36293034, 2022). "TPA-associated genes differentially expressed in the Bhas 42 CTA included markers such as RAN, MTHFD2, WT1, and AURORA-A, which lead to carcinoma formation and malignant transformation in humans and test animals." (PMID 35328637, 2022). "Wilms tumor 1 (WT1) was initially discovered as a tumor suppressor gene, but later it was also identified as an oncogene in various cancers." (PMID 34944812, 2021). "There are also complex interactions between WT1 and the FoxO, AMPK and Hippo signaling pathways and hub genes in other cancers." (PMID 34692659, 2021). "However, the functions of each of the four WT1 isoforms in cancer cells remain unclear." (PMID 34845427, 2021). "Frequently used markers include mesothelial markers (calretinin or Wilms tumor 1 (WT1)) and carcinoma-related markers (CEA, CD15, Ber-EP4, MOC-31, and TTF-1)." (PMID 34439085, 2021). "To evaluate whether FDG PET-CT could detect anti-cancer immune response caused by cancer vaccine therapy, we performed a retrospective analysis of FDG PET-CT imaging of patients who were treated with Wilms Tumor 1 (WT1) vaccine therapy in Osaka University during July 2008 and June 2018." (PMID 32991475, 2020). "In collaboration with WT1/Early Growth Response 1 (EGR1), Bcl2 contributes to dysregulation of calcium homeostasis and signaling in cancer cells." (PMID 32856872, 2020). "FGF2 and CHEK4 are up-regulated while the expression of CHEK1, WT1, MDM2, BARD1, BMP2, BAMBI, and SOD2, have been reported to be down-regulated in several cancer subtypes, including CRC." (PMID 31623294, 2019). "Among the cancer driver genes expressed in K-RMS-1 we found increments in the expression of BAX, RASD1, WT1, AKT1, cMYC and NOTCH." (PMID 30745580, 2019). "Cancer testis antigens and oncofetal antigens like MAGE, WT1 as well as alpha-fetoprotein are expressed in a wild range of different cancer cells, but limited in normal tissues except for embryonic cells or germ cells 161-164." (PMID 31695801, 2019). "In the matched-control breast tissue from patients with cancer, linear regression analysis revealed that the NPI increases as the number of WT1-positive cells decreases." (PMID 30374123, 2018). "Although genes like WT1, GATA3 and PHOX2B were frequently hypermethylated in several cancer types, others were restricted to certain tissue types." (PMID 28581523, 2017). "In humans, peptide vaccination studies with HLA-A24/WT1235-243 epitopes have been well characterized in the literature to elicit WT1-specific CD8+ T-cell responses in adult and children cancer patients." (PMID 28435676, 2017). "Collectively, these results demonstrate that WT1 is necessary for transcriptional upregulation of SHMT1, which mediates cancer-promoting activity of WT1." (PMID 28288142, 2017). "On the top of the list of tumour antigens suitable for DC-based cancer therapy is WT1 protein (overexpressed in AML) or highly immunogenic MUC-1 (overexpressed and/or hypoglycosylated in numerous cancer types)." (PMID 27212807, 2016). "Our findings suggest that WT1 and p63 act as oncogenes in SCCHN, affecting multiple genes involved in cancer cell growth." (PMID 25929687, 2015). "As Wilms’ tumor 1 (WT1) molecules are expressed in various types of solid tumors, DC vaccination targeting this molecule for cancer patients has priority as an immunotherapy." (PMID 28536414, 2015).
cancer (continued). "As a novel technique, RNAa has successfully activated several target genes in various human diseases including those involved in cancers, such as p21, E-cadherin, VEGF, WT1 and several others." (PMID 25435951, 2015). "Subsequently, it has been shown that WT1 expression in epicardiocytes induces Snail, a master regulator of EMT, which is also expressed during carcinoma progression." (PMID 25025131, 2014). "We found that low-WT1 Ab level in plasma was related to improved survival in patients diagnosed at stages III–IV and grade 3 carcinomas." (PMID 24715586, 2014). "WT1 and MUC1 reportedly have the first and second highest priorities, respectively, for cancer vaccines among the currently available cancer antigens." (PMID 24649223, 2013). "WT1 and MUC1 were ranked as the two most highly immunogenic peptides in a variety of cancer tissues." (PMID 24649223, 2013). "Frequently altered genes involved in transcription factor activity in various cancer types include homeobox (HOX) genes, paired box (PAX) genes, and Wilms tumor suppressor gene (WT1)." (PMID 23033966, 2012). "High performance of our resequencing approach is also illustrated by the fact that we identified mutations in known candidate drivers in T-ALL that were included in the collection of known cancer genes such as NOTCH1, FBXW7, PTEN, PHF6, WT1 and PIK3CA." (PMID 22675565, 2012). "Thus, the control of the WT1 gene may differ in cancers from different sites." (PMID 21063414, 2010). "Among the 86 tumors, pT3 carcinoma samples expressed FGFR1 and WT1 proteins more frequently than pT2 samples." (PMID 17137506, 2006). "The simultaneous activation of WT1-specific CD4+ Th1 cells and CD8+ CTLs may be essential when treating patients with advanced-stage cancer." (PMID 39737308, 2024). "Among them, CCDC28B showed strong positive and negative staining contrast in cancer cells, CCL5 exhibited moderate positive and negative staining contrast in cancer cells, and WT1 showed weak positive and negative staining contrast in cancer cells." (PMID 38676834, 2024). "In addition, WT1 knockdown led to decreased phosphorylation of AKT, consistent with reported effects in other cancer models." (PMID 38190392, 2024). "According to our analysis of clinical trials, WT1 cancer vaccines are safe to use and do not worsen side effects when used in conjunction with chemotherapy, which usually involves the drug GEM." (PMID 38665761, 2024). "Combined treatment with standard anticancer therapy and the WT1/MUC1-DC vaccine may induce antitumor immune responses during vaccination and appears to provide some clinical benefit to patients with cancer." (PMID 38336778, 2024). "Therefore, it is recommended to use panels consisting of at least two carcinoma markers (such as pCEA BER-EP4, MOC-31, Claudin 4, HEG1) and two mesothelial markers (such as WT1, calretinin, CK5/6, D2-40)." (PMID 39407894, 2024). "Currently, drug development strategies targeting WT1 primarily focus on cancer vaccines, and there is a lack of antagonistic drugs specifically targeting WT1." (PMID 37765274, 2023).
cancer (continued). "Wilms’ tumor 1 (WT1) is widely recognized as one of the most prevalent cancer antigens and holds the top rank according to the cancer antigen pilot prioritization: criteria and sub-criteria definitions and weightings, which was published by the National Cancer Institute (NCI) in the United States." (PMID 37765274, 2023). "During the phase I clinical trial involving hTERT- and WT-1-specific CD8+ T cells, approximately 43% of patients exhibited hTERT-reactive CD8+ T cells (61 patients out of 142 cancer patients), and 30–35% displayed WT-1-specific CD8+ T cells (data not shown)." (PMID 37761976, 2023). "Various peptide sequences from the WT1 antigen have been identified as immunogenic and capable of evoking sustained cytotoxic T-cell (CTL) responses that, in turn, target and kill WT1-expressing cancer cells." (PMID 36900251, 2023). "We found that the overexpression of WT1 in carcinoma was specific to CDC73Mut patients but not present in CDC73WT patients." (PMID 37121965, 2023). "The ABL1-I418T, PIK3CB-R231H, CHEK2:c.-4C > T, BRCA2-P3292L, ABL1-E459G, PRPF8-G1796R, PHF6-R274Q, WT1-R435X and ATM-C117Y variants were potentially important cancer variants which were not actionable." (PMID 35896598, 2022). "Actually, an emerging chemotherapy-resistance mechanism, driven by WT1 downregulation, due to transcript cleavage via HTRA2, a protease overexpressed under cytotoxic therapy, has been shown to increase cancer cell survival, based on C-MYC/JUNB upregulation, which is normally repressed by WT1." (PMID 35453662, 2022). "Although the molecular mechanisms that account for the increased expression of WT1 in these cancers are not fully characterized, it has been reported that the proximal WT1 promoter contains a hypoxia-responsive element (HRE), which is a binding site of HIF-1." (PMID 35465313, 2022). "The prime evidence supporting this role is the overexpression of wild-type WT1 in a variety of human cancers of both hematological and non-hematological origin." (PMID 35328637, 2022). "To comprehensively evaluate our predictions, we used several benchmark gene sets, including EWSR1-WT1 fusion-related genes, DSRCT-related genes, and cancer pathway genes as well as a set of genes whose promoter regions were found to be peak binding sites of WT1 by ChIP-Seq38." (PMID 35379887, 2022). "Calretinin, D2-40 (podoplanin), Wilms’ tumor-1 (WT1) and CK5/6 are recommended for distinguishing mesothelial differentiation, whereas the common markers of carcinoma are BerEP4, CEA (carcinoembryonic antigen), pancytokeratins and, more recently, claudin-4 as a marker of adenocarcinoma." (PMID 35205798, 2022). "Although diffuse and strong WT1 cytoplasmic staining has been observed in several benign and malignant tumors, there is no information available about the expression of WT1 in DFPS." (PMID 33445443, 2021). "The apparent adverse interaction between NRAS and WT1 in AML and T-ALL might be due to these different roles of WT1 in cancer development and warrants further investigation." (PMID 34615983, 2021). "This combination vaccine could be given to patients whose cancer expresses HAGE and WT1 in parallel with existing therapies in order to decrease the chance of disease progression and relapse." (PMID 34262856, 2021). "Additionally, transcripts of genes related to pathways regulating cell survival and migration such as mTOR, c-Myc, COX 2, NF-κB (p65), bcr/abl, WT1, TGF-β1 and MMP-935,36 were also found to be downregulated, excepting PTEN in cancer cells exposed to CMRP." (PMID 33436696, 2021). "In immunohistochemistry, the cancer cells were immunoreactive for WT1, PAX8, and CA125, and negative for GATA3, mammaglobin, and gross cystic disease fluid protein-15." (PMID 33593410, 2021). "In immunohistochemistry, the cancer cells were immunoreactive for WT1, PAX8, and CA125, and negative for GATA3, mammaglobin, and gross cystic disease fluid protein-15 (GCDFP15)." (PMID 33593410, 2021).
cancer (continued). "Our previous study has found that YPFS could regulate p62/TRAF6 signaling, WT1/MVP axis and mTORC2/AKT signaling, which account the anti-MDR effects and anti-cancer effects both in vivo and in vitro models." (PMID 34135758, 2021). "CDX2 is usually expressed, whereas WT1, ER, and PR expression is absent, unlike endometrioid (ER+) and serous (ER+ and WT1+) carcinomas." (PMID 33919741, 2021). "WT1 exon displayed significantly increased methylation in cancer tissue compared to nonmalignant breast tissue." (PMID 32736539, 2020). "As an example, WT1 gene is not among the top hub genes of the WT-module because of its involvement in different cancer types." (PMID 31988326, 2020). "Therefore, degrasyn holds promise as cancer therapeutic agent in PDAC with high expressions of USP5 and WT1." (PMID 31845546, 2020). "David A. Scheinberg's laboratory selected a ScFv fragment that is specific for the WT1 RMF peptide/HLA-A*0201 complex found on many human cancers, they also engineered the scFv fragment to a full length human monoclonal antibody to target cancer cells." (PMID 31695801, 2019). "Besides peptides, other monovalent vaccines were developed for HER2+ BC using other cancer-specific antigens such as MUC-1 vaccine in metastatic setting, WT1 vaccine for neodjuvant patients and gangliosides in adjuvant treatment, with some encouraging results." (PMID 31665051, 2019). "WT1 negative, PR positive suggests an EM carcinoma, although the sensitivity is only approximately 70%." (PMID 31248002, 2019). "Statistical analysis was undertaken to ascertain whether the expression pattern of WT1 differed between the HER2-positive (n = 17) and HER2-negative cancers (n = 40)." (PMID 30374123, 2018). "Subgroup analysis by cancer types revealed that WT1 overexpression did not have an unfavorable effect on OC in univariate model (metaHR = 1.26, 95% CI = 0.66–2.38) and multivariate model (metaHR = 1.13, 95% CI = 0.32–4.06)." (PMID 29995811, 2018). "The Wilms' tumor 1 (WT1) antigen is expressed in solid and hematological malignancies, but not healthy tissues, making it a promising target for cancer immunotherapies." (PMID 28435676, 2017). "Here, the induction of WT1‐specific CD8+ T‐cell responses after allogeneic stem cell transplantation and/or donor lymphocyte infusions demonstrated the immunogenicity of WT1 in cancer patients." (PMID 25882672, 2015). "Next, the ratio of Ex4a(+)WT1 isoform to 17AA(+) WT1 isoform was determined by RT-PCR using Ex4-forward and Ex6-reverse primer pair in WT1-expressing cancer cell lines (LU99B and K562) and determined to be approximately 1/2 and 1/4 in LU99B and K562 cancer cells, respectively." (PMID 26090994, 2015). "In our work, the exposure of cancer cells to a combination of paclitaxel and TCPOBOP increased WT1 gene expression compared to that with treatment with paclitaxel or TCPOBOP alone, making combination treatment of CAR agonists with paclitaxel a potentially interesting option for NSCLC therapy." (PMID 24959746, 2014).
cancer (continued). "We have detected aberrant methylation in five cancer-related CpGIs, that is estrogen receptor-α [ESR1 (+244bp)], O6-methylguanine-DNA methyltransferase [MGMT (-463bp)], Wilms' Tumor-1 [WT-1 (-146bp)], Breast Cancer 2 [BRCA2 (+138bp)] and Hermen Antigen [CD44 (+28bp)]." (PMID 22011321, 2011). "The impact of WT1 gene expression on the clinical outcome of this cancer was not demonstrated by previous studies." (PMID 16606472, 2006). "Notably, we demonstrated that ENG+ CAFs, WT1+ CAFs, and CAPs shared phenotypic characteristics with mesenchymal populations in the healthy developing pancreas, whereas LRRC15+ CAFs represented a cancer-specific phenotype." (PMID 40215177, 2025). "Accumulating clinical results suggest that major advances, such as the incorporation of DCs pulsed with WT1 and/or MUC1 peptide vaccines and standard anticancer therapies into the clinician’s therapeutic arsenal, can prolong OS and/or PFS in many patients with cancer." (PMID 38336778, 2024). "Therefore, vaccines using DCs pulsed with WT1 and MUC1 peptides (WT1/MUC1-DC) may represent a viable and minimally invasive treatment option for a range of cancers." (PMID 39737308, 2024). "By stimulating WT1-specific cytotoxic and helper T cells, DSP-7888 in combination with anti-programmed cell death protein 1 (PD-1) demonstrated its ability to elicit strong antitumoral activity toward cancer cells expressing high levels of WT1 during in vitro and in vivo preclinical trials." (PMID 38173713, 2023). "The role of WT1 in controlling the balance between the mesenchymal and epithelial state of the cells might provide a critical link between WT1 and EMT, which is a key process for the metastasis of carcinomas." (PMID 35465313, 2022). "These include pathways common to many types of cancer (DNA damage-response pathway, epithelial-mesenchymal transition) as well as receptors that have been identified as overexpressed or activated specifically in DSRCT as targets of the EWS-WT1 transcription factor (LRRC15, NTRK3)." (PMID 34869013, 2021). "Mesothelial cells are generally positive for calretinin, thrombomodulin, cytokeratin 5/6, WT1, D2-40, vimentin, HBME-1 and CD44H, while polyclonal and monoclonal carcinoembryonic antigen, Ber-EP4, Leu-M1, CA-125, B72.3, PAX8, MOC 31, CA19-9 and ER are the most common markers of carcinoma." (PMID 34068638, 2021). "Whilst it was demonstrated that global WT1 expression was elevated in cancer samples, this increase could not be attributed to increased expression in vascular endothelial cells (despite increased vascular density in these specimens)." (PMID 30374123, 2018). "Although the prognostic and immunotherapeutic role of WT1 has been demonstrated in a variety of nongynecological cancer types, the prognostic value of WT1 expression in gynecological tumor still remains unclear." (PMID 29995811, 2018). "WT1 knockdown by antisense oligomers, ribozyme, or PEI- RNAi suppresses cell proliferation and induces apoptosis, suggesting that removal of WT1 might has anti-cancer effect in multiple types of cancers." (PMID 27821145, 2016). "Our results indicate that WT1 induces features of both EMT and MET in ccRCC and suggest that it may regulate phenotypic plasticity by promoting an epithelial-mesenchymal hybrid differentiation state in cancer." (PMID 25025131, 2014). "Furthermore, patients with high-WT1 IgG level in plasma and positive WT1 staining in cancer tissue specimens had a shorter survival than those with high-WT1 IgG Ab level but negative WT1 staining." (PMID 24715586, 2014). "Expression of the WT1 gene could not be examined by immunohistochemistry because of the difficulty in obtaining enough cancer tissue to perform this test." (PMID 24228711, 2013). "Finally, WT1 is expressed at high levels in most adult cancers studied, though expression has not been detected in the normal tissue counterparts." (PMID 22216009, 2011).